COX6C (cytochrome c oxidase subunit 6C)
Description:
Component of the cytochrome c oxidase, the last enzyme in the mitochondrial electron transport chain which drives oxidative phosphorylation. The respiratory chain contains 3 multisubunit complexes succinate dehydrogenase (complex II, CII), ubiquinol-cytochrome c oxidoreductase (cytochrome b-c1 complex, complex III, CIII) and cytochrome c oxidase (complex IV, CIV), that cooperate to transfer electrons derived from NADH and succinate to molecular oxygen, creating an electrochemical gradient over the inner membrane that drives transmembrane transport and the ATP synthase. Cytochrome c oxidase is the component of the respiratory chain that catalyzes the reduction of oxygen to water. Electrons originating from reduced cytochrome c in the intermembrane space (IMS) are transferred via the dinuclear copper A center (CU(A)) of subunit 2 and heme A of subunit 1 to the active site in subunit 1, a binuclear center (BNC) formed by heme A3 and copper B (CU(B)). The BNC reduces molecular oxygen to 2 water molecules using 4 electrons from cytochrome c in the IMS and 4 protons from the mitochondrial matrix.
Tractability: Small molecule: a structure with a bound ligand is known. Antibody: UniProt predicts a signal peptide or a membrane-spanning region. PROTAC: ubiquitination databases record sites on it; its protein half-life has been measured.
Gene: Protein-coding gene on chromosome 8 (99,873,200 to 99,893,759, reverse strand). Ensembl gene ENSG00000164919.
Subcellular location: Mitochondrion inner membrane
Subcellular location (Human Protein Atlas): Mitochondria
Pathways (Reactome):
Metabolism: Complex IV assembly; Respiratory electron transport
Cellular responses to stimuli: Cytoprotection by HMOX1
Gene Ontology:
Molecular function: protein binding
Biological process: cellular respiration; generation of precursor metabolites and energy; mitochondrial electron transport, cytochrome c to oxygen; oxidative phosphorylation
Cellular component: mitochondrial inner membrane; mitochondrial membrane; mitochondrion; respiratory chain complex IV; mitochondrial intermembrane space; membrane
Genetic constraint (gnomAD): Loss-of-function variants: 2 observed, 5.06 expected, observed/expected ratio (o/e) 0.4, 90% interval 0.16 to 1.23. That is too few expected variants to judge how well the gene tolerates losing a copy. Missense variants: 64 observed, 68.55 expected, observed/expected ratio (o/e) 0.93, 90% interval 0.76 to 1.15. Synonymous variants: 25 observed, 24.87 expected, observed/expected ratio (o/e) 1.01, 90% interval 0.73 to 1.4.
Homologues: Orthologues: chimpanzee COX6C (99% identical), macaque COX6C (88% identical), guinea pig COX6C (77% identical), mouse Cox6c (75% identical), pig COX6C (75% identical).
Diseases named in the same sentence as COX6C in open-access papers:
COX6C is named in the same sentence as 51 diseases in open-access papers, as found by Europe PMC text mining. Sharing a sentence is not in itself a finding about the gene and the disease. The quoted sentences say what the papers report.
breast carcinoma (18 papers, 2017 to 2025). "Accumulating evidence demonstrates that COX6C is closely associated with the tumorigenesis and prognosis of breast cancer, gastric cancer, melanoma, and many solid tumors." (PMID 36551283, 2022). "Recent studies demonstrate that Cytochrome c oxidase subunit 6c (COX6C) has a particular association with breast cancer, esophageal cancer, thyroid tumors, prostate cancer, uterine cancer, and melanoma." (PMID 36251702, 2022). "Specifically, EVs with mitochondrial inner membrane proteins MT-CO2 (mitochondrially encoded cytochrome c oxidase I) and COX6c (cytochrome c oxidase subunit 6C) were detected in the plasma of melanoma patients as well as in ovarian and breast cancer patients." (PMID 33819075, 2021). "Notably, NDUFA4 is associated with immune modulation, PD-L1 expression, and breast cancer prognosis, while altered expression of COX6C and COX7C, subunits of cytochrome c oxidase, is linked to poor cancer prognosis." (PMID 40618351, 2025). "Interestingly, two mitochondrial inner membrane proteins MT-CO2 (encoded by the mitochondrial genome) and COX6c (encoded by the nuclear genome) were highly prevalent in the plasma of melanoma patients, as well as in ovarian and breast cancer patients." (PMID 31497264, 2019). "COX6C is linked to drug resistance, while TFF3 serves as a marker of differentiation and progression in breast cancer, particularly in DCIS, where it reflects a differentiated and secretory phenotype." (PMID 41182757, 2025). "CXCL14 encodes secreted proteins involved in immuno-regulatory and inflammatory processes, which promotes tumor growth in breast cancer, and COX6C serves as a bio-marker for cancer therapy." (PMID 38783355, 2024). "It has been demonstrated that COX6c plays a crucial role in the identification of hormone-responsive breast cancer or estrogen receptor (ER)+ subtypes." (PMID 35879322, 2022). "COX6c helps to understand not only the etiology of prostate and breast cancers but also other cancers, including follicular thyroid cancer, uterine myomas, and retroperitoneal lipoma, which aids in tumor diagnosis." (PMID 35879322, 2022). "COX6C, a mitochondrial inner membrane protein, was highly prevalent in the plasma of melanoma patients as well as in ovarian and breast cancer patients." (PMID 33318294, 2020). "In addition, increased expression of COX6C was also observed in cancerous tissues from patients with prostate cancer or estrogen receptor positive (ER+) breast cancer." (PMID 38242874, 2024). "Conversely, genes highly expressed in PIPET_LumB, such as STC2, COX6C and DHRS2, may be associated with tumor invasion, metastasis and epithelial–mesenchymal transition in breast cancer." (PMID 38819254, 2024). "To test whether this increased concentration of MT-CO2/COX6c in plasma is specific for melanoma, we applied the same assay to plasma from ovarian and breast cancer patients." (PMID 31497264, 2019). "Furthermore, COX6C upregulation was associated with poor overall survival (OS) in basal‐like breast cancer, while poor OS and distant metastasis‐free survival (DMFS) in HER2‐positive breast cancer." (PMID 36594618, 2023). "The CXCL14, COX6C, and CRISP3 have been verified are highly expressed genes of invasive dual carcinoma (IDC) in breast cancer." (PMID 39764614, 2024). "To evaluate the role of COX6C and DHRS2 in breast cancer cells, we utilized short hairpin RNA (shRNA) to generate T‐47D, MDA‐MB‐231, and MCF‐7 cell lines with low COX6C or DHRS2 expression." (PMID 36594618, 2023). "Downregulation of COX6C and DHRS2 notably inhibited the proliferation of breast cancer cells." (PMID 36594618, 2023). "Recently, many investigations have reported the unusual level of COX6C in different cancerous and non-cancerous disease conditions such as diabetes, uterine leiomyoma, prostate cancer, melanoma tissues, breast cancer, and follicular thyroid cancer." (PMID 37482618, 2023).
breast carcinoma (continued). "Taken together, these data demonstrated that the downregulation of COX6C and DHRS2 might inhabit cell proliferation, migration, and EMT in breast cancer." (PMID 36594618, 2023). "In the transwell migration assay, migrated cells transfected with shIL4I1 were remarkably decreased by 60% or more compared with control, indicating high levels of COX6C and DHRS2 could facilitate breast cancer invasion." (PMID 36594618, 2023). "In breast cancer MCF7 cells, estradiol was shown to increase levels of mitochondrial COX6c and ATP synthase, which may lead to drug resistance of cancer cells." (PMID 29416685, 2018). "Kaplan–Meier analysis showed that the overall survival rates were significantly lower in breast cancer patients with than without amplification of one of these genes (log rank test; NDRG1, P = 0.0554; UBR5, P = 0.0122; MYC, P = 0.0094; EXT1, P = 0.0103; NBN, P = 0.0030; and COX6C, P = 0.0073)." (PMID 28977883, 2017).
melanoma (12 papers, 2019 to 2025). A malignant, usually aggressive tumor composed of atypical, neoplastic melanocytes. "Extracellular vesicles (EVs) obtained from metastatic tissue from melanoma patients have higher levels of mitochondrial membrane proteins, including MT-CO2 (encoded by the mitochondrial genome) and COX6c (encoded by the nuclear genome), than EVs isolated from non-melanoma-derived cells." (PMID 35879322, 2022). "Overexpression of COX6C has been reported in breast, prostate, thyroid, gastric cancers, melanoma, and uterine leiomyoma." (PMID 41157129, 2025). "Jang isolated EVs from melanoma tissue and discovered two proteins from mitochondrial membrane, MT-CO2 and COX6c, which were also found in the plasma of melanoma, breast, and ovarian cancer patients, therefore can be potential biomarkers for liquid biopsy." (PMID 38598014, 2024). "Previous studies have shown that COX6C can cause chronic kidney disease (CKD), diabetes, carcinoma, melanoma and other diseases." (PMID 35933451, 2022). "High luminescence signals for MT-CO2 were detected both in healthy and melanoma patients, but luminescence signals from COX6c were elevated in melanoma patients compared to healthy control." (PMID 31497264, 2019). "MT-CO2 and COX6c in melanoma and other tumors exemplify their role as liquid biopsy biomarkers." (PMID 41157129, 2025). "COX6C is differentially expressed in thyroid cancer and melanoma." (PMID 38196829, 2023). "The same group also showed that two mitochondrial inner membrane proteins: cytochrome c oxidase subunit 2 (MT-CO2) and cytochrome c oxidase subunit 6C (COX6c) are enriched in the plasma of melanoma patients as well as in tumor tissues-derived EVs compared to healthy controls." (PMID 32331267, 2020). "Importantly, we detected significantly higher levels of combined MT-CO2 and COX6c signal in plasma of melanoma patients compared with healthy controls (p = 0.0038)." (PMID 31497264, 2019). "Interestingly, more than 50% of melanoma-specific membrane proteins that are identified in this study was found in plasma EV proteome from health individuals and 25% of overlapping proteins, including MT-CO2 and COX6c, are mitochondrial proteins." (PMID 31497264, 2019). "In addition, we could identify the presence of MT-CO2/COX6c signals directly in plasma from melanoma patients, without any preceding EV isolation procedure." (PMID 31497264, 2019).
prostate carcinoma (6 papers, 2022 to 2025). A carcinoma that arises from epithelial cells of the prostate gland. "Functionally, elevated COX6C expression enhances oxidative phosphorylation and supports tumor proliferation, as demonstrated in gastric and prostate cancer cells." (PMID 41157129, 2025). "In situ hybridization has shown that COX6c mRNA expression is upregulated in prostate tumor tissue and is the highest in scattered epithelial cells of prostate carcinoma." (PMID 35879322, 2022). "Together, these data indicate that the expression pattern of COX6c may serve as a useful marker to study the alteration of energy metabolism in cancer cells and help the diagnosis of prostate cancer." (PMID 35879322, 2022).
Uterine leiomyoma (4 papers, 2015 to 2025). The presence of a leiomyoma of the uterus. "In uterine leiomyomas, HMGA2 fusion transcripts were reported with various sequences including COX6C (8q22.2), ALDH2 (12q24.12), CCNB1IP1 (14q11.2), RAD51B (14q24.1), and RTVL-H 3_ LTR (21q21.2)." (PMID 28591699, 2017). "Furthermore, COX6C participates in oncogenic rearrangements, including gene fusions with HMGA2 in uterine leiomyoma and translocations in retroperitoneal lipomas and thyroid carcinomas." (PMID 41157129, 2025).
Alzheimer disease (3 papers, 2019 to 2024). A progressive, neurodegenerative disease characterized by loss of function and death of nerve cells in several areas of the brain leading to loss of cognitive function such as memory and language. "For example, COX6C is downregulated in blood samples from familial hypercholesterolemia patients as well as temporal and parietal cortices in patients with Alzheimer’s disease, while is significantly elevated in the glomeruli of diabetic nephropathy rats." (PMID 38242874, 2024).
COVID-19 (3 papers, 2022 to 2023). A disease caused by infection with severe acute respiratory syndrome coronavirus 2. "In our study, rs12548840 in the intron of COX6C was identified to be associated with NAbs level of COVID-19 vaccine immunization." (PMID 36451823, 2022). "Moreover, COX6C is downregulated in patients with mild COVID-19 infection compared with controls but is upregulated in patients with severe COVID-19 compared with patients with mild illness." (PMID 36451823, 2022).
atherosclerosis (2 papers, 2022 to 2025). A disease characterized by the build-up of fatty material and calcium deposition in the arterial wall resulting in partial or complete occlusion of the arterial lumen. "Of them, Ctnnd2, Dap, Marchf6, Cmbl, Sdc2, Cpq, Stk3, Vps13b, Cox6c, Grhl2, Fzd6, Cthrc1, Lrp12, and Zfpm2 showed associations or had functions related to atherosclerosis or obesity." (PMID 40362477, 2025). "Since mitochondria are also a prime cellular source of reactive oxygen species (ROS), the underlying mechanism may entail the ROS accumulation in COX6c, which contributes to the increase in oxidative stress, ultimately hastening the evolution of hypercholesterolemia and atherosclerosis." (PMID 35879322, 2022). "Moreover, the downregulation of COX6c expression in blood samples from familial hypercholesterolemia patients suggests that aberrant expression of COX6c may result in the development of atherosclerosis through the OXPHOS pathway." (PMID 35879322, 2022).
colorectal cancer (2 papers, 2022). A primary or metastatic malignant neoplasm that affects the colon or rectum. "Similar to COX6C, COX5B was found to promote cell growth and reduce anticancer drug susceptibility in colorectal cancer cells, which may lead to unfavorable postoperative outcomes for patients with colorectal cancer." (PMID 36551283, 2022).
diabetic nephropathy (2 papers, 2022 to 2024). "Interestingly, expression of COX6C is significantly upregulated in rat diabetic nephropathy models." (PMID 35445133, 2022).
esophageal cancer (2 papers, 2022 to 2023). A primary or metastatic malignant neoplasm involving the esophagus. "qRT-PCR detection demonstrated increased expression of MPC1, COX6C, CYB5R3, CASP7, and CYCS in esophageal cancer patients." (PMID 38196829, 2023). "Our results showed that the levels of MPC, COX6C, CYB5R3, CASP7, and CYCS were significantly upregulated in tumor tissues compared with adjacent non-tumor tissues in esophageal cancer patients." (PMID 38196829, 2023). "In addition, we found by qRT-PCR that the levels of MPC1, COX6C, CYB5R3, CASP7, and CYCS in tumor tissues of esophageal cancer patients were significantly higher than adjacent non-tumor tissues, suggesting that these genes may have some value in clinical diagnosis and prognosis." (PMID 38196829, 2023).
familial hypercholesterolemia (2 papers, 2022 to 2024). An inheritable form of hyperlipidemia, in which there are excess lipids in the blood. "The analysis of KEGG signaling revealed significant enrichment of differentially expressed genes, including the COX6c gene in the OXPHOS pathway in familial hypercholesterolemia patients." (PMID 35879322, 2022).
multiple myeloma (2 papers, 2022). "COX6C is differentially expressed in multiple myeloma (MM) and is associated with MM prognosis." (PMID 36451823, 2022). "Additionally, relapsed/refractory myeloma patients expressed significantly higher expression of NDUFB8, NDUFA6, COX6C, and USMG5 than newly diagnosed patients." (PMID 36551283, 2022). "Our results indicate that NDUFB8, NDUFA6, COX6C, COX5B, and USMG5 might influence the immune microenvironment of multiple myeloma patients, as well as the response to treatment and prognosis of patients with this disease." (PMID 36551283, 2022).
Obesity (2 papers, 2021 to 2025). Accumulation of substantial excess body fat. "Skeletal muscle ETC protein content has been shown to be progressively diminished, including reductions in COX6C, in nondiabetic individuals with obesity and individuals with T2DM in comparison to lean counterparts." (PMID 34690929, 2021).
adenoma (1 paper, 2021). A neoplasm arising from the epithelium. "Additionally, when we compared proteomic profiling of adenomas, to the proteomic expression of colon biopsies, there were some moieties (ATP5J2, DPAGT1, PTPLB, HERC1, and COX6C) that were down-regulated in both." (PMID 33799486, 2021).
bile acid synthesis disorders (1 paper, 2018). "Cholic acid is used to target COX6C in treatment of adults and children with bile acid synthesis disorders such as Zellweger Syndrome56." (PMID 29545597, 2018).
Cerebral ischemia (1 paper, 2024). Restriction of arterial blood supply to the brain associated with insufficient oxygenation to support the metabolic requirements of the tissue. "Another study has shown that COX6C involvement in cerebral ischemia proteins may allow the identification of putative biomarkers or therapeutic targets for ischemic stroke." (PMID 39655053, 2024).
esophageal adenocarcinoma (1 paper, 2025). A malignant tumor with glandular differentiation arising predominantly from Barrett mucosa in the lower third of the esophagus. "High expression of AZIN1-AS1, COX6C, MMP12 and PVT1 might be associated with a worse survival outcome both in TCGA ESCC and esophageal adenocarcinoma (EAC) datasets." (PMID 40569942, 2025).
Hypertension (1 paper, 2024). The presence of chronic increased pressure in the systemic arterial system. "Similarly, ZNF12, the regulator of ATP5J as well as COX6C, was also identified as hypertension-associated QTL in rats." (PMID 38410507, 2024).
hypopotassemia (1 paper, 2018). "Next, we also observed associations of various phenotypes such as hyposomality (abnormal levels of electrolytes), hypopotassemia, chloride levels and septicemia with the gene Cytochrome oxidase 6 C (COX6C)." (PMID 29545597, 2018).
influenza infection (1 paper, 2022). "Further, some researchers have speculated that COX6C is an important component of the apoptotic pathway and may play a regulatory role in the early stages of influenza infection." (PMID 36357826, 2022).
ischemia (1 paper, 2022). A hypoperfusion of the BLOOD through an organ or tissue caused by a PATHOLOGIC CONSTRICTION or obstruction of its BLOOD VESSELS, or an absence of BLOOD CIRCULATION. "In contrast, increased mitochondrial function promoted increased Cox6c protein expression in a mouse model of ischemia." (PMID 36012153, 2022).
lung adenocarcinoma (1 paper, 2024). A carcinoma that arises from the lung and is characterized by the presence of malignant glandular epithelial cells. "COX6C localizes on the region and its expression is notably enhanced that driven by amplification in lung adenocarcinoma." (PMID 38242874, 2024). "Collectively, we suggested that copy amplification-mediated COX6C upregulation might serves as a prospective biomarker for prognosis and targeting therapy in patients with lung adenocarcinoma." (PMID 38242874, 2024).
lymph node metastasis (1 paper, 2023). "Fisher's exact test showed the expression of both COX6C and DHRS2 are significantly related to the presence of lymph node metastasis." (PMID 36594618, 2023).
Pleural effusion (1 paper, 2025). The presence of an excessive amount of fluid in the pleural cavity. "We also identified pleural effusion predictive gene signatures, including TMPRSS3, MS4A7, NAPSA, and IGFBP2, while liver metastasis predictive markers included WFDC2, HSPB1, COX6C, APOE, and TUBA1A." (PMID 39955556, 2025).